BSPRY (B-box and SPRY domain containing)
Description:
May regulate epithelial calcium transport by inhibiting TRPV5 activity.
Synonyms: FLJ20150
Tractability: Antibody: UniProt places it where antibodies can reach, with medium confidence. PROTAC: ubiquitination databases record sites on it.
Gene: Protein-coding gene on chromosome 9 (113,349,520 to 113,371,233, forward strand). Ensembl gene ENSG00000119411.
Subcellular location: Cytoplasm; Membrane
Subcellular location (Human Protein Atlas): Nucleoplasm; Cytosol
Gene Ontology:
Molecular function: ubiquitin protein ligase activity
Biological process: innate immune response
Cellular component: cytosol; cytoplasm; membrane
Genetic constraint (gnomAD): Loss-of-function variants: 34 observed, 37.22 expected, observed/expected ratio (o/e) 0.91, 90% interval 0.69 to 1.22. The upper end of that interval is the gene's LOEUF score, 1.22, which puts it in group 5 of 6, group 1 being the genes least tolerant of losing a copy. Missense variants: 523 observed, 497.99 expected, observed/expected ratio (o/e) 1.05, 90% interval 0.98 to 1.13. Synonymous variants: 224 observed, 213.74 expected, observed/expected ratio (o/e) 1.05, 90% interval 0.94 to 1.17.
Homologues: Orthologues: chimpanzee BSPRY (99% identical), macaque BSPRY (97% identical), pig BSPRY (89% identical), dog BSPRY (87% identical), guinea pig BSPRY (79% identical), mouse Bspry (79% identical), rat Bspry (77% identical), tropical clawed frog bspry (54% identical). Paralogues in human: TRIM16 (20% identical), TRIM11 (19% identical), TRIM58 (18% identical), TRIM14 (18% identical), TRIM21 (18% identical), TRIM17 (18% identical), TRIM35 (18% identical), MID2 (17% identical), TRIM65 (17% identical), TRIM39 (17% identical), TRIM4 (17% identical), TRIM10 (16% identical), and 68 more.
Diseases named in the same sentence as BSPRY in open-access papers:
BSPRY is named in the same sentence as 4 diseases in open-access papers, as found by Europe PMC text mining. Sharing a sentence is not in itself a finding about the gene and the disease. The quoted sentences say what the papers report.
parathyroid adenomas (1 paper, 2014). "Among signal transduction proteins, we observed a significant decrease of BSPRY expression in parathyroid adenomas." (PMID 25164318, 2014). "Taking into account the regulatory role of the BSPRY and the involvement in cell proliferation of TRPV5/TRPV6, we investigated the presence of both channels in parathyroid adenoma and in parathyroid normal gland, either at mRNA or protein level." (PMID 25164318, 2014).
cancer (3 papers, 2012 to 2025). A tumor composed of atypical neoplastic, often pleomorphic cells that invade other tissues. "Similarly, BSPRY has been a top predictive gene in at least 4 independent risk models and correlation-based prognostic tools in renal and other cancers." (PMID 41188181, 2025). "Other five genes, including BSPRY, C8ORF47, FAM3B, HOOK1 and REG1A, were clustered in Model 16 and significantly decreased during cancer progression." (PMID 30598639, 2018). "The involvement of BSPRY in cancer stem cells biology has not been explored." (PMID 23482333, 2012).
tumor (2 papers, 2012 to 2025). "A high expression of BSPRY in tumor cells was associated with poor OS in DLBCL patients according to GERS." (PMID 23482333, 2012). "A further important gene for differentiating these tumor types is the BSPRY gene, which regulates epithelial calcium transport by inhibiting TRPV5 activity." (PMID 40457272, 2025). "The COGS model includes genes such as AP1M2, PLCL1, PLCL2, ITGB3 and BSPRY, whose altered expression could contribute to tumorigenesis and tumor progression." (PMID 40457272, 2025).
BSPRY also shares sentences with these, for which no sentence is quoted: adenoma (1 paper).